IL18 (interleukin 18)
Diseases named in the same sentence as IL18 in open-access papers (continued):
Sharing a sentence is not in itself a finding about the gene and the disease.
chronic obstructive pulmonary disease (21 papers, 2013 to 2025). A chronic and progressive lung disorder characterized by the loss of elasticity of the bronchial tree and the air sacs, destruction of the air sacs wall, thickening of the bronchial wall, and mucous accumulation in the bronchial tree. "MMP-8 and IL-18 are pro-inflammatory markers associated with chronic obstructive pulmonary disease (COPD)." (PMID 34127548, 2021). "Previous studies suggest that the downstream products of NLRP3 inflammasomes such as IL-1β or IL-18 are associated with the pathophysiology of smoke-driven chronic obstructive pulmonary disease (COPD) although direct evidence to link NLRP3 protein with the disease is sparse." (PMID 28056996, 2017). "SCFAs (acetate, propionate, and butyrate) can enhance the expression of GPR43 while downregulating the expression of NLRP3, IL-18, and IL-1β, thereby strengthening the mucosal immune function of the gut and lungs in rats with chronic obstructive pulmonary disease." (PMID 40906358, 2025). "Besides, IL-12 and IL-18 converted ILC2 into ILC1 in patients with chronic obstructive pulmonary disease (COPD)." (PMID 33193374, 2020). "In viral infections and patients with chronic obstructive pulmonary disease (COPD), ILC2s have been documented to convert to an ILC1-like phenotype characterised by T-bet expression and IFNg production in response to the cytokines IL-1b, IL-12 and IL-18." (PMID 38745765, 2024). "In chronic obstructive pulmonary disease (COPD) patients, smokers and the end stage of COPD has higher serum level of IL-18 in those who were not smoking and lower stage." (PMID 34840991, 2021).
endotoxemia (21 papers, 2011 to 2023). "Arndt and colleagues suggest that, in animal models endotoxemia-related lung injury was associated with increased IL-18 levels in both blood and lung tissue, and this could explain in part a possible relationship of pulmonary hemorrhage and IL-18." (PMID 25977887, 2015). "As detected, high levels of pro-inflammation cytokines IL6, IL1β and IL18 in endotoxemia colon were reversed by JQ1 pretreatment." (PMID 33679744, 2021). "Since endotoxemia is an infection-induced systemic inflammatory response, the expressions of pro-inflammatory factors IL6, IL18, and IL1β in endotoxemia colon were calculated by Q-PCR and western blot." (PMID 33679744, 2021). "IL‐18 originally named as “interferon‐c‐inducing factor,” and IL‐18 potentiated mortality in both neonatal sepsis and endotoxemia through the induction of IL‐17A." (PMID 33378581, 2021). "In mice subjected to endotoxemia, IL-37 inhibited plasma IL-1β (−78% compared to wild-type animals) and IL-18 (−61%)." (PMID 31936823, 2020). "To investigate the effect of IL-37 on the generation of mature IL-18, we also analyzed LPS-induced plasma IL-18 in mice subjected to endotoxemia." (PMID 31936823, 2020). "As both MIF and NLRP3 have been implicated in the pathogenesis of septic shock, we next investigated the effects of COR123625 on serum IL-1β and IL-18 in a mouse model of LPS-induced endotoxemia." (PMID 29884801, 2018). "The proinflammatory cytokine interleukin (IL)-18 is an important mediator of the organ failure induced by endotoxemia." (PMID 29261164, 2017). "The serum levels of IL-6, IL-8, and IL-18, were reported to be increased secondary to systemic endotoxemia, in patients with alcoholic liver disease and steatohepatitis." (PMID 23097664, 2012). "IL-18-KO neonatal mice were highly protected from polymicrobial infection, and blocking IL-17A reduced IL-18-potentiated mortality to neonatal sepsis and endotoxemia." (PMID 36769133, 2023). "Cholinergic anti-inflammatory pathways are potently activated by electrical VNS, as demonstrated in previous studies that prevented the release of pro-inflammatory cytokines such as TNF-⍺, IL-1β, IL-6, and IL-18 during endotoxemia, and in patients receiving tragus stimulus following acute MI." (PMID 37801130, 2023). "Only inhibition of both IL-18 and IL-1β completely protects against mortality in a murine model of lethal endotoxemia, and combined blockade of IL-18 and IL-1β has been successfully implemented in a genetic form of MAS resulting from NLRC4 inflammasome hyperactivity." (PMID 35190900, 2022). "Because IL-18 regulates the synthesis of TNF-α, IL-1β, IL-8 and MIP-1α, removal of IL-18 may have a beneficial effect in lethal endotoxemia in naive mice." (PMID 32503314, 2020). "IL-18 is also a pleiotropic cytokine related with both innate and acquired immune responses and one of its native stimuli is subclinical endotoxemia, indicated by low to moderately elevated circulating lipopolysaccharide (LPS) derived from gram-negative bacteria." (PMID 21437204, 2011). "Both the accumulation of inflammation cytokines especially IL18 and IL1β, and the activation of NLRP3/ASC/Caspase 1 inflammasome complex in damaged colon indicated that endotoxemia-induced colonic mucosa injury might be related with inflammation-related pyroptosis." (PMID 33679744, 2021).
ischemia (21 papers, 2010 to 2025). A hypoperfusion of the BLOOD through an organ or tissue caused by a PATHOLOGIC CONSTRICTION or obstruction of its BLOOD VESSELS, or an absence of BLOOD CIRCULATION. "IL-18 acts as the proinflammatory cytokine inducing tissue damage, inflammation, and apoptosis, and increased IL-18 levels are associated with myocardial injury after ischemia or infarction." (PMID 35222806, 2022). "Results from animal studies indicate that IL-18 is involved in inflammation caused by ischemia." (PMID 30366444, 2018). "Although the expression of caspase-1/11 and IL-1β/IL-18 is controversial due to the differences in subjects and the time of ischemia, consistent with our study, the expression of GSDMD and GSDMD-N increased during myocardial ischemia." (PMID 35783187, 2022). "The mechanism research showed that the levels of NLRP3, caspase-1, IL-1β and IL-18 were all increased in rat brain with I/R injury, which was ischemia for 1 h and then reperfusion for 24 h." (PMID 34445481, 2021). "The data suggested that sRAGE suppressed the transcription of IL-1β and IL-18 in primary cultured cardiomyocytes following ischemia-reperfusion injury." (PMID 34912499, 2021). "Active IL-18 requires cleavage of its precursor form by caspase-1; inhibition of caspase-1 also attenuated the depression in contractile force after ischemia (from 35% of control to 75.8% in treated atrial muscle)." (PMID 24115947, 2013). "Tubular IL-18 expression is upregulated in murine models of lupus nephritis and renal ischaemia." (PMID 22518072, 2012). "IL-18, and S100A12 may be important driving forces of inflammatory processes caused by ischemia." (PMID 30366444, 2018). "Moreover, endogenous IL-18 is induced by IL-1β via caspase-1 under ischemic conditions in human myocardial tissue and that inhibition of caspase-1 reduces the processing of endogenous precursors of IL-18 and IL-1β and thereby prevents ischemia-induced myocardial dysfunction." (PMID 24115947, 2013). "Colchicine mitigates inflammation triggered by ischemia by indirectly inhibiting NLRP3 oligomerization, which reduces the production of IL-1β and IL-18." (PMID 40149903, 2025). "In a mouse model in which ischemia was pharmacologically induced, it was observed that TREM-1 promotes the production of IL-1β, IL-18, IL-6, CXCL-2, MCP-1, and CXCL-1 in microglia." (PMID 39062850, 2024). "Moreover, as per our findings, ischemia led to an increase in the HDAC9 expression in the brain of wild type mice, while the loss of HDAC9 was observed to suppress the release of IL-1β, IL-6, IL-18, and TNF-α in the mouse cortex, hippocampus, and hypothalamus after I/R injury." (PMID 33584204, 2020). "Consistently, we found that ischemia-induced TREM-1 promoted IL-1β, IL-18, IL-6, CXCL-2, MCP-1, and CXCL-1 productions in microglia as well as the expression of MPO and ICAM-1 following ischemic injury." (PMID 31324751, 2019). "IL-18 and S100A12 are likely to be driving forces in the inflammatory response of RVO complicated by ischemia." (PMID 30366444, 2018). "Serum samples were collected and heart-type fatty acid binding protein (H-FABP), ischemia modified albumin (IMA), interleukin-1β (IL-1β), and interleukin-18 (IL-18) were measured to observe whether Sevoflurane anesthesia had protective effect on myocardium." (PMID 34765646, 2021). "Similarly, EPO also reduced post-ischemic upregulated mRNA levels of IL-1β at both reperfusion timepoints, while the other cleavage product of inflammasomes, IL-18, did not appear to be affected by either ischemia or EPO administration." (PMID 34628598, 2022). "In a rat model of permanent focal ischemia by embolisation of TiO2-spheres we assessed key features of post-ischemic neuroinflammation by the means of histology, immunocytochemistry of glial activation and influx of hematogeneous cells, and quantitative PCR of TNF-α, IL-1, IL-18, and iNOS mRNA." (PMID 21171972, 2010).
lupus nephritis (21 papers, 2008 to 2025). Glomerulonephritis in the context of systemic lupus erythematosus. "Further research to investigate the association of IL-18 and sFas and their exact role in induction or maintaining of lupus nephritis is required." (PMID 23577265, 2013). "More importantly, the overwhelming reliance on cross-sectional designs significantly restricts the ability to infer causal relationships between IL-18 and lupus nephritis (LN), or to capture dynamic changes in IL-18 levels relative to disease activity, treatment response, and pathological outcomes." (PMID 41142814, 2025). "Elevated serum interleukin-18 (IL-18) in lupus nephritis (LN) correlates with renal histopathological severity, highlighting its potential as a prognostic biomarker and pathogenic driver." (PMID 41142814, 2025). "Among 18 studies investigating IL-18 in lupus nephritis (LN), only three concurrently measured serum IL-18BP levels." (PMID 41142814, 2025). "Significantly increased expression of cytokines in the glomerulus, including IFN-γ, IL-12, IL-18 and IL-10, was correlated with disease activity indices in patients with lupus nephritis." (PMID 39478861, 2024). "For example, IL-18 protein was reported to be expressed in intercalated cells from the late distale tubule to the collecting duct of the kidney and tubular epithelial cells, and IL-18 protein expression was inducible in glomeruli in Lupus nephritis." (PMID 35204131, 2022). "In agreement, human studies reveal that patients with lupus nephritis had increased concentration of serum IL-18, and kidney biopsies showed IL-18 positive glomeruli compared to normal subjects." (PMID 36032110, 2022). "As expected, the serum level of Th1/Th2 cytokines IL-18/IL-4 was significantly higher in LN-IV compared to other groups of lupus nephritis LN-III (p = 0.001), LN-V (p = 0.005), and healthy control (p < 0.0001)." (PMID 27738386, 2016). "Serum levels of Th1 cytokines (IFN-γ, IL-18, and IL-12p70) and Th17 cytokines (IL-17A and IL-6) were significantly elevated in lupus nephritis-IV when compared with healthy control." (PMID 27738386, 2016). "Based on our findings, we propose that in lupus nephritis, IL-18 and sFas have interrelated effects on proteinuria." (PMID 23577265, 2013). "A large and growing body of literature expressed the role of IL-18 and sFas in lupus nephritis apart from each other, and some investigators referred to the local production of IL-18 in glomeruli resulting in local effects in the pathogenesis of LN." (PMID 23577265, 2013). "Neutrophil serine proteases act as alternative processing enzymes of pro-inflammatory cytokines IL-1β and IL-18 in vivo and modulate other inflammation-related control mechanisms such as progranulin inactivation in small vessel vasculitis and lupus nephritis." (PMID 21892962, 2011). "This meta-analysis was performed to quantitatively assess the relationship between circulating IL-18 levels and lupus nephritis (LN) in SLE patients, incorporating stratified analyses by renal histopathological classifications (WHO classes II, III, IV, and V) to evaluate disease progression markers." (PMID 41142814, 2025). "Urinary levels of IL-18 and VCAM-1 were reported to be increased and associated with pathological events in lupus nephritis, so MAIT cells may also migrate into inflamed tissues in SLE." (PMID 28288675, 2017). "IL-18, a pro-inflammatory cytokine in the IL-1 superfamily, critically contributes to SLE and lupus nephritis (LN)." (PMID 41142814, 2025). "Th1 and Th17 cytokines (IL-18, IFN-γ, IL-12p70, IL-6, and IL-17A) were considerably expressed in the serum of lupus nephritis IV patients in comparison to the healthy control." (PMID 27738386, 2016). "Besides, correlations between IL-18 and SLE severity, incidence of lupus nephritis had been pointed out12." (PMID 33633218, 2021). "However, only IL18 and IL6 were higher in class IV versus class III lupus nephritis." (PMID 27738386, 2016).
lupus nephritis (continued). "In addition, only IL18 and IL6 were higher in class IV versus class III lupus nephritis." (PMID 27738386, 2016). "Compared to those in SLE patients without renal damage, patients with lupus nephritis (LN) exhibited lower mRNA levels of NEK7, NLRP3, and ASC but higher levels of Caspase-1, IL-1b, and IL-18." (PMID 30202244, 2018).
AIDS (20 papers, 2010 to 2025). A syndrome resulting from the acquired deficiency of cellular immunity caused by the human immunodeficiency virus (HIV). "A new monogenic AIDs characterized by IL-18 hypersecretion have been associated with cytoskeletal abnormalities." (PMID 34262554, 2021). "Numerous agents have been developed to target inflammasome products IL-1β and IL-18 for treating AIDs." (PMID 38666950, 2024). "Among patients with monogenic AIDs, the maximum concentrations of IL18 are in patients with FMF, and the minimum concentrations - in patients with CAPS." (PMID 36096831, 2022). "The IL-1 cytokine family (IL-1α, IL-1β, IL-1Ra, IL-18, IL-36Ra, IL-36α, IL-37, IL-36β, IL-36g, IL-38, IL-33) was defined to be principally responsible for the inflammatory nature of polygenic AIDs." (PMID 33708123, 2020). "This combination of observations led us to the hypothesis that enhancement of inflammasome-dependent, IL18-driven production of IFN-γ by non-CD4 cells may be a route to control acute toxoplasmosis in AIDS." (PMID 32753607, 2020). "However, it has been hypothesized that chronic excessive production of IL-18 contributes to AIDS pathogenesis, since in vitro studies have shown that IL-18 improves HIV-1 replication in both monocytes and T-cells." (PMID 40452022, 2025). "In addition, increased inflammation, as noted by elevated levels of pro inflammatory cytokines such as IL-18 (data not shown), has been linked to development of AIDS." (PMID 34721397, 2021). "Significant associations were observed between baseline plasma levels of CD20+ EVs and baseline plasma levels of prognostic biomarkers of AIDS-NHL: sCD27, CXCL13, sIL-2Rα/sCD25, sTNF-RII, sCD163, IL-18, LBP, and EndoCab IgM." (PMID 40646161, 2025). "More recently, several independent groups have identified monogenic autoinflammatory diseases (AIDs) with recurrent MAS and chronic elevation of total IL-18." (PMID 38183056, 2024). "IL-18, CCL2, TRAF6 and IL-12Rβ1 were upregulated in both AIDS and IBD patients compared to controls." (PMID 26475133, 2015). "In the present study, we examined how baselinies plasma levels of CD20+ extracellular vesicles (EVs) relate to these previously characterized biomarkers of AIDS-NHL, such as IL-10, CXCL13, IL-10, BAFF, sCD14, sTNF-RII, sIL-2Rα/sCD25, IL-18, and CCL12-MCP-129–31." (PMID 40646161, 2025). "Furthermore, CD20+ EVs showed significant positive correlations with potential prognostic biomarkers of AIDS-NHL29,30,40,41 at baseline: sCD27, CXCL13, sIL-2Rα/sCD25, sTNF-RII, sCD163, IL-18, LBP, and EndoCab IgM." (PMID 40646161, 2025). "IL-1β and IL-18, potent pro-inflammatory cytokines and primary outputs of the activated NLRP3 inflammasome, play crucial roles in the development of various inflammatory and AIDs." (PMID 38666950, 2024). "Collectively, the results presented so far raise the prospect that, if the ability of non-CD4 cells to invoke inflammasome-dependent, IL18-driven production of IFN-γ can be enhanced, it may be possible to control acute toxoplasmosis in AIDS." (PMID 32753607, 2020). "To evaluate further the role of translocated microbial products in driving immune activation in chronic SIV infection, we assessed the distribution and co-localization of interleukin-18 (IL-18) and LPS in the gut-draining MesLN in SIV-uninfected and chronically SIV-infected Non-AIDS RMs." (PMID 20808901, 2010). "Consistent with a role for translocated microbial products inducing immune activation and IL-18 expression, Ahmad and colleagues recently described significantly elevated levels of IL-18 in the serum of HIV-infected/AIDS patients compared to those of HIV-seronegative healthy individuals." (PMID 20808901, 2010). "Our findings support repeated measure of IL-18 in cART-naïve persons for early identify patients that would not responds to CD4 gains despite virological suppression to prevent clinical progression to AIDs and non-AID events." (PMID 37937297, 2023).